HLA-F (major histocompatibility complex, class I, F)
Diseases named in the same sentence as HLA-F in open-access papers (continued):
Sharing a sentence is not in itself a finding about the gene and the disease.
tumor (48 papers, 2015 to 2025). "High HLA-F surface expression has been associated with tumor size and a poor clinical outcome in breast cancer and with cell invasion in gastric cancer patients." (PMID 39766165, 2024). "HLA-F expression is associated with the ability of tumor cells to escape the body’s immune killing capacity, and its reduced expression suggests metastasis of tumor cells." (PMID 37864213, 2023). "B cells, MKI67+ T cells and dysfunctional T cells, interact with tumor-associated macrophages (TAMs), which are enriched by preoperative chemotherapy, through HLA-F-LILRB2 and HLA-DPB1-NRG1 pathways in the cell niche of primary tumors." (PMID 36465392, 2022). "Notably, HLA-F expression is negatively associated with overall survival 9, 13, indicating that HLA-F might play a role in tumorigenesis or tumor progression." (PMID 33867844, 2021). "Thus, HLA-F expression may be associated with aggressive tumor behavior, and the promotion of tumor cell invasion and metastasis." (PMID 25435979, 2015). "Conversely, DCs in solitary primary tumours showed high expression of MHC class I molecules (HLA‐F, HLA‐E, HLA‐C, HLA‐B, HLA‐A)." (PMID 39601163, 2024). "In terms of HLA expression, HLA-A, HLA-B, HLA-C, HLA-E, HLA-F, HLA-G, and HLA-J were significantly more highly expressed in C2 than in C1, indicating that tumour subtypes differ in the activation of immune cells." (PMID 37691922, 2023). "HLA-F has been found to mainly play a role in immune tolerance and tumor progression that is distinct from the role of presenting antigens of HLA-Ia molecules." (PMID 36672208, 2023). "This study identifies circCRIM1 as a new tumor suppressor that inhibits tumor immune evasion through a competitive combination with IGF2BP1 to destabilize HLA-F mRNA." (PMID 36672208, 2023). "The expression of class I HLA molecules, which are responsible for antigen presentation to tumor-killing T-cells, including HLA-A, HLA-B, HLA-C, HLA-E, HLA-F, and B2M, was downregulated in 7, 8, 5, 10, 5, and 14 patients, respectively." (PMID 37152992, 2023). "We found that HSPA5 and PSME2 were significantly upregulated whereas HLA-F was significantly downregulated in tumor tissues compared with normal tissue (p < 0.0001)." (PMID 34257557, 2021). "Validation analysis indicated that HLA-C, HLA-DPA1, HLA-E, HLA-F and HLA-G were associated with HCC prognosis of overall survival (all P ≤ 0.05, elevated 0.988 and 0.997 multiples compared to non-tumor tissues, respectively)." (PMID 31602270, 2019). "In conclusion, the present study demonstrated that HLA-F expression was associated with poor survival in HCC patients, and is correlated with tumor cell invasion and metastasis." (PMID 25435979, 2015). "Although the precise role of HLA-F in reproduction and during pregnancy has yet to be systematically studied, recent research has shed light on the relationship between this molecule and tumor progression." (PMID 40251569, 2025). "HLA-E and HLA-F might help tumor cells evade immunity by interacting with inhibitory receptors on NK cells." (PMID 40104502, 2025). "The proteomic analyses revealed that the combination treatment significantly downregulated tumour-promoting genes such as HLA-F, TRIAP1, TMBIM6, and ENTPD8, suggesting reduced mitochondrial integrity and immune escape, thereby enhancing apoptotic susceptibility." (PMID 41516237, 2025). "The roles regarding tumor development and the progression of HLA-F and HLA-H are still unclear." (PMID 39766165, 2024). "Tumors can deploy different mechanisms to escape from NK cells and differential expression of HLA-E and HLA-F may act synergistically to promote tumor survival." (PMID 38281021, 2024). "In contrast, CD80/CD86-CTLA4 and HLAF-LILRB1/2 were found in both tumour subtypes." (PMID 38782901, 2024).
tumor (continued). "HLA-F may activate or inhibit NK and CD8+T cells by physically interacting with killer-cell immunoglobulin-like receptors (KIRs) such as KIR3DL2, KIR2DS4, and KIR3DS1, indicating that HLA-F may potentially contribute to tumor immune evasion." (PMID 36672208, 2023). "Whether HLA-E and HLA-F expression promotes immune evasion from NK and T cells or contribute to expand the HLA repertoire on tumor cells remains to be established." (PMID 38318504, 2023). "The expression of HLA-F was downregulated in the high-risk group, whereas, the expression of HLA-DQB2 was upregulated in the high-risk group, indicating that this possibly led to tumor immune evasion (P-value < 0.05)." (PMID 35144613, 2022). "However, in addition to acting as an immunoregulatory molecule, the roles of HLA-F in tumor development are unclear." (PMID 33867844, 2021). "In this scenario, intracellular HLA-F expression was frequently observed in resting cells, such as peripheral blood B cells, B cell lines, and tissues, such as the fetal liver, adult tonsils, and thymus, and in malignant lesions or tumor cell lines." (PMID 31134067, 2019). "However, interaction and signal transduction between the receptors and the tumor cell expressed HLA-F antigens remain to be explored." (PMID 31134067, 2019). "Univariate and multivariate Cox proportional regression analyses showed that HLA-F expression (hazard ratio: 3.87; 95% confidence interval (CI): 1.29–11.58; p = 0.016) and tumour stage (hazard ratio: 4.31; 95% CI: 1.01–18.46; p = 0.049) were independent factors for LRFS." (PMID 30510890, 2018). "In conclusion, in the present study, positive HLA-F expression was associated with poor survival in HCC patients, and may be correlated with invasion and metastasis of tumor cells." (PMID 25435979, 2015). "We hypothesize that HLA-F expression may also enable tumor cells to escape from recognition by the host immune system." (PMID 25435979, 2015). "HLA-F expression is exhibited in different manners in various types of tumor." (PMID 25435979, 2015). "Angiogenesis-related genes (FLT1, KDR, SPARC, INSR, ANGPT2, and FLT4) and MHC-I molecules (HLA-A, HLA-B, HLA-C, HLA-E, and HLA-F) were highly expressed in cluster 3 ECs, indicating that the cells may function as antigen-presenting cells and promote tumor parenchymal angiogenesis." (PMID 37533434, 2023). "Specifically, the involvement of human leukocyte antigen (HLA) class I molecules (such as HLA‐A, HLA‐B, HLA‐C, HLA‐E and HLA‐F) and CD8A/B was consistently observed in the interactions between malignant cells and CD8 T cells in both tumour types." (PMID 39601163, 2024). "Correspondingly, lower expression of HLA-F, more CD8+ T cell and NK cell infiltration, and more apoptosis tumor cells in tumors of the circCRIM1-overexpressing group were detected with the IHC assay." (PMID 36672208, 2023). "This analysis underscores the precise involvement of HOXB6, HLA-F, and CAMKV in tumor progression through T cell activation processes in the luminal A subtype." (PMID 38012271, 2023). "Most MHC I molecules, including HLA-A, HLA-C, HLA-E, HLA-F, TAP1, TAP2, and TAPBP (all P < 0.05), were upregulated in PTPRD/PTPRT mutant patients, indicating enhanced anti-tumor immunity in PTPRD/PTPRT mutant patients." (PMID 36248841, 2022). "Results showed that the expression levels of HPSE, HLA-F, and SELL were downregulated in most tumor tissues with high CDYL2b expression compared to the expression levels in matched normal breast tissues." (PMID 32373210, 2020). "Four genes belong to the HLA family: HLA-DQA1, HLA-DRB1, HLA-DQB1, and HLA-F, which were significantly overexpressed in RCC tumor tissues compared with paired adjacent normal tissues." (PMID 25784652, 2015). "We observed consistently higher expression levels of MHC class I genes (HLA-A, HLA-B, HLA-F, HLA-E, B2M) in tumor cells from non-progressors to progressors." (PMID 39753553, 2025).
tumor (continued). "Interestingly, only 10 genes, including the MHC Class I complex gene HLA-F, were found to be responsible for downregulating ICD scores, potentially suppressing the immune response against tumor cells undergoing immunogenic cell death." (PMID 40777132, 2025). "The expression levels of B2M(p = 2.926e-05), HLA-C(p = 2.628e-03), HLA-E(p = 5.5166e-08), HLA-F(p = 9.376e-03), TAP1(p = 1.972e-09), TAP2(p = 1.245e-04) and TAPBP (p = 2.652e-12)in tumor tissues of dMMR patients were significantly higher than those of pMMR patients." (PMID 36527024, 2022). "Additionally, miR-9, which functions as a tumor suppressor in NPC55, positively regulated the expression of MHC class I genes (such as HLA-B and HLA-F) in NPC12." (PMID 32308549, 2020). "HLA-F on B-cells was found to induce immune tolerance in tumor cells by interacting with inhibitory receptor ILT-2 and ILT-4 of the natural killer or CTLs, thereby blocking their cytotoxicity for the tumor cells." (PMID 28210261, 2017). "Furthermore, antigen-presenting molecules and immune molecular interactions, such as those between HLA-A, HLA-B, HLA-C, HLA-E, and HLA-F with CD8A and CD8B, appeared to be significantly up-regulated in tumor tissues, while their presence in normal tissues was comparatively diminished." (PMID 40723292, 2025). "Interestingly, this population of cells may also be involved in tumor antigen presentation, since genes for MHC-I molecules (HLA-A, HLA-B, HLA-C, HLA-E, and HLA-F) were highly expressed in this cluster." (PMID 37533434, 2023). "Also, TGFB1, ENG, B2M, HLA-F, SELPLG, and ITGB2 were significantly increased in tumor-associated macrophages, compared with those nontumor-associated macrophages." (PMID 36249427, 2022). "Whether HLA-F is expressed on the tumor cell surface as a monomer or with B2m was not clarified." (PMID 38390869, 2024). "In addition, HLA-DQA1 and HLA-F showed prognostic values for overall survival, and HLA-A, HLA-C, HLA-DPA1 and HLA-DQA1 showed prognostic values for recurrence-free survival (all P ≤ 0.05, elevated 0.927, 0.992, 1.023, 0.918, 0.937 multiples compared to non-tumor tissues, respectively)." (PMID 31602270, 2019). "Among the genes upregulated in the tumor compartment (79 PanCK+ segments from 10 patients) of non-responders, the most differentially expressed were IDO1, HLA-F, S100A8, and S100A9." (PMID 37835599, 2023). "Notably, these include endogenous non-tumour ligands for the previously orphan immune checkpoint receptor VISTA, comprising the non-classical MHC molecules HLA-E and HLA-F." (PMID 35922511, 2022).
cancer (34 papers, 2011 to 2026). A tumor composed of atypical neoplastic, often pleomorphic cells that invade other tissues. "Whereas knowledge of the role of HLA-F in cancer is sparse, HLA-E expression is also seen in several cases of cancers associated with immune suppression." (PMID 32560316, 2020). "Elevated HLA-F expression has been found in cancer lesions and peripheral blood, which was associated with poor survival in cancer patients." (PMID 31134067, 2019). "Immunosuppressive signaling nodes between the MHC class I molecule, HLA-F, on both cancer basal cells and CAFs and the inhibitory receptor, leukocyte immunoglobulin like receptor B1 (LILRB1), on monocyte/macrophages, were also noted in older patients." (PMID 41188599, 2025). "By exploring the specific functions of HLA-E, HLA-F, HLA-G, and HLA-H in various cancers, the authors aim to highlight their importance in the immune system’s interaction with tumors." (PMID 39766165, 2024). "There are several reports on the expression of HLA-F on cancer cells, and in the light of what has been discussed so far, there is an imminent need for anti-HLA-F monospecific mAbs such as HLAFS-27 and HLAFS-28 potentially for therapeutic purposes." (PMID 38390869, 2024). "Immune-suppressive signaling nodes between the class I molecule, HLA-F, on both CAFs and cancer basal cells with the inhibitory receptor, leukocyte immunoglobulin like receptor B1 (LILRB1), on monocyte/macrophages were also noted in older TNBC patients." (PMID 39483921, 2024). "Many HLA molecules, for example, HLA-E, HLA-F, HLA-G, HLA-H and HLA-DR were reported to be overexpressed on cancer cells." (PMID 36778644, 2023). "Previous studies have found that HPSE and SELL can promote the invasion and metastasis of cancer cells, and the expression of HLA-F is closely related to the invasion of cancer 56-58." (PMID 32373210, 2020). "While several studies have found significant HLA-F expression in several cancer types, the data are even less conclusive." (PMID 31013867, 2019). "Auto-antibodies against leukocyte antigen F (HLA-F) were also detected in patients with various cancer types compared to healthy individuals." (PMID 22761861, 2012). "Furthermore, HLA-F was upregulated in cancer cells from the S components, which was shown to be correlated with the upregulation of LILRB1/LILRB2 in macrophages." (PMID 35874770, 2022). "Another relevant positive biomarker for all 18 cancer types is B2M → HLA-F." (PMID 34430923, 2021). "The impact of HLA-F expression in cancer is a matter of controversy." (PMID 32978482, 2020). "Moreover, HLA-F in this list has already been reported as detectable in the serum of various cancer patients using indirect ELISA." (PMID 22761861, 2012). "Moreover, CD247, CD3G, HLA‐B, HLA‐C, and HLA‐F took part in various pathways, including Th1 and Th2 cell differentiation, PD‐L1 expression and PD‐1 checkpoint pathway in cancer, Th17 cell differentiation, antigen processing presentation, allograft rejection, and cell adhesion molecular." (PMID 35037412, 2022). "These regulatory RNAs included the anti-sense RNAs HLA-F, LIFR, PRKAR2A, ZEB1, and long intergenic non-coding RNAs (LINC) 887, 1431, 2482, as well as microRNAs (MIRs) 22HG and 3648, which are associated with viral inflammation and cancer and cellular proliferation, respectively." (PMID 33763387, 2021). "To achieve a comprehensive and objective evaluation of MHC-I expression in cancers, we developed a MHC-I signature score based on GSVA of eight MHC-I family genes, including HLA-A, HLA-B, HLA-C, HLA-D, HLA-E, HLA-F, HLA-H, and B2M." (PMID 39408874, 2024). "Our results demonstrated that 5 of the 6 up-regulated mRNAs in “HTLV-1 infection pathway” increased (ICAM1, WNT2B, MYC, HLA-F and TGF-β1) and 3 of the 5 down-regulated mRNAs in “Pathways in cancers” decreased (CDH1, PTENP1, HSP90AA1)." (PMID 24367666, 2013).
cancer (continued). "In recent years, non-classical HLAs—including HLA-E, HLA-F, HLA-G, and HLA-H—have emerged as critical players in the immune landscape of cancer due to their diverse and less conventional functions in immune modulation." (PMID 39766165, 2024). "HLA-F and HLA-E negatively coexpressed with LINC01614 in more than six cancers." (PMID 38655053, 2024). "LILRB1 and LILRB2 expressed in macrophage subsets were found to interact with the nonclassical human leukocyte antigen HLA-F expressed in cancer cells." (PMID 39669575, 2024). "There are classical forms, HLA-A, HLA-B, and HLA-C, and non-classical forms, HLA-G, HLA-E, HLA-F, and HLA-H, of this protein; both have been identified in cancer with diverse roles." (PMID 34359613, 2021). "When cancer cells (i.e., A549, HCC827, CNE2 and HONE1 cells) were transiently transfected with miR-19a or miR-19b-1 mimics, qRT-PCR data revealed a general downward trend in the expression profile of the MHC Class I genes (such as HLA-B, HLA-F, HLA-G)." (PMID 32308549, 2020). "Regarding the correlations between RORC expression and MHC molecules (which are closely associated with cancer occurrence and development), RORC expression exhibited the strongest positive correlation with HLA-F in ACC, and the strongest negative correlation with B2M in UVM." (PMID 36186454, 2022). "However, we notice that HLA genes are amongst the most highly enriched genes in both cancers; furthermore, they are consistently overexpressed in BCC compared to PDAC by a factor of 2-10 with the exception of HLA-E and HLA-F, suggesting that PDAC suffers from much more severe MHC-I suppression." (PMID 35178072, 2021). "Moreover, among the enriched genes in the group of cancer areas in the dHGP, we detected many genes known to enhance inflammatory reactions in cancer by promoting the NFκB pathway (IKBKB, FKBP4), activating lymphocytes (TNFSF9, HLA-F) or recruiting neutrophils (DPEP1)." (PMID 36691028, 2023). "Human leukocyte antigen (HLA)-F, a non-classical HLA-class I molecule, has attracted attention as an important immunosuppressive molecule in recent years, although the clinical relevance of HLA-F expression in cancer patients remains unclear." (PMID 25435979, 2015). "This study demonstrated that miR-19a or miR-19b-1 overexpression in cancer cells led to a general downward trend in the expression profile of MHC Class I molecules (such as HLA-B, HLA-E, HLA-F, HLA-G or HLA-J), which has never been reported in other physiological and pathological processes." (PMID 32308549, 2020). "Similarly, higher or comparable levels of expression of the non-classical genes, HLA-E, HLA-F, and HLA-G, were observed in HPV+ cancers with respect to normal control tissues in the HNSC cohort." (PMID 28891951, 2017).
infection (10 papers, 2019 to 2025). The state of being infected such as from the introduction of a foreign agent such as serum, vaccine, antigenic substance or organism. "This study also found that infection of CD4+ T cells with HIV increased transcription of the gene encoding HLA-F; our finding suggests this may be due to an epigenetic mechanism." (PMID 31324826, 2019). "Increased HLA-F expression has been reported after infection with Japanese Encephalitis virus, HIV-1 (early in infection), HCV, and BK polyomavirus (BKpV)." (PMID 41425562, 2025). "Although many viruses have developed mechanisms to avoid HLA expression during infection, HLA-F expression is upregulated during HIV infection while its interaction with KIR3DS1 is diminished." (PMID 30941482, 2019). "During course of infection the amount of HLA-F remains consistent though its interaction with the receptor occurs to be diminished." (PMID 31717259, 2019). "HLA-F expression may be reduced on CD4+ T cells late in infection with HIV-1, impacting KIR3DS1 binding and NK cell activation." (PMID 41425562, 2025). "Interestingly, increased protein levels of HLA-F and interaction with NK cells have been indicated after infection with BK polyomavirus, HIV, and HCV." (PMID 36713229, 2022). "MHC variants showed no important associations between class I antigen-presentation genes (HLA-A, HLA-B, and HLA-C) and nonclassical HLA class I genes (HLA-G, HLA-E, and HLA-F) in symptomatic infection susceptibility." (PMID 34650566, 2021). "Taken together, this suggests that HLA-F may play a role in infection control." (PMID 41425562, 2025). "The mAb 3D11 did not detect HLA-F HCs on the cell surface of normal B cells or on any normal peripheral blood lymphocytes but detected cell surface HLA-F only when cells were in an activated state (caused by inflammation, injury, infection, or in the presence of proinflammatory cytokines)." (PMID 38390869, 2024). "Despite this, the full biological peptide selection criteria of HLA-F have not yet been thoroughly investigated especially in infection situations." (PMID 30941482, 2019).
infectious disease (2 papers, 2019 to 2026). A disorder directly resulting from the presence and activity of a microbial, viral, or parasitic agent in humans. "In the present review, we will focus on the potential roles of HLA-F in immune modulation and its relevance in infectious disorders." (PMID 31134067, 2019).
bacterial infections (1 paper, 2025). "Whereas Class2 uniquely included pathways related to bacterial infections (e.g., E. coli, Salmonella) together with actin-cytoskeleton and T-cell modules (e.g., ACTB, PFN1, RAC2, PIK3CD, CD3D/CD3G, STING1, TRADD, CASP8, BCL2, HLA-F)." (PMID 41394852, 2025).